IGFBP3 (insulin like growth factor binding protein 3)
Diseases named in the same sentence as IGFBP3 in open-access papers (continued):
Sharing a sentence is not in itself a finding about the gene and the disease.
breast carcinoma (continued). "Intracellular trafficking of IGFBP-3 with nuclear localisation in T47D breast cancer cells is explicable through a carboxy-terminal nuclear localisation signal and importin-β-mediated nuclear transport[B15,20,21]." (PMID 15642160, 2005). "Increasing levels of IGFBP-3 in breast cancer tissues correlate with poor prognostic features, as demonstrated in four studies in vivo through enzyme-linked immunosorbent assay and immunoradiometric assay." (PMID 15642160, 2005). "Although previous studies in vivo have suggested a tumour-related upregulation of IGFBP-3 levels, clinical studies have yet to determine IGFBP-3 epithelial protein expression in breast cancers; this is the first IHC study." (PMID 15642160, 2005). "Complex IGFBP-3 modulation of breast cancer growth has prompted several studies to examine levels of IGFBP-3 in breast cancer tissues in relation to clinicopathological characteristics and patient outcome." (PMID 15642160, 2005). "Nuclear localisation of IGFBP-3 has been described in several cell lines in vitro, including breast cancer cells." (PMID 15642160, 2005). "Further, IGFBP-3 inhibits oestradiol-stimulated cell proliferation in breast cancer cell lines, with the potential to accentuate ceramide and paclitaxel-induced apoptosis directly." (PMID 15642160, 2005). "The aim of this first immunohistochemical study was to evaluate breast epithelial IGFBP-3 expression in relation to clinicopathological parameters and prognosis in breast cancer." (PMID 15642160, 2005). "By contrast, in IGF-unresponsive Hs578T breast cancer cells, IGFBP-3 is predominantly growth-inhibitory and pro-apoptotic[B11,27]." (PMID 15642160, 2005). "Tumour-related upregulation of IGFBP-3 levels in aggressive breast cancers is only partly explicable by the described findings in vitro." (PMID 15642160, 2005). "The IGFs are modulated by a family of six high-affinity IGF binding proteins, of which IGFBP-3 predominates in serum and is upregulated in breast cancer cell lines, including breast epithelium." (PMID 15642160, 2005). "The findings from this small prospective study are consistent with a moderate increase in breast cancer risk associated with high levels of IGF-I, after adjustment for IGFBP-3." (PMID 15756268, 2005). "In conclusion we have demonstrated that IGFBP-3 can exert differential effects on normal versus breast cancer epithelial cells." (PMID 12085194, 2002). "We also investigated the effects of TGF-β-induced IGFBP-3 on C2-induced death in the Hs578T breast cancer cells." (PMID 12085194, 2002). "The bioavailability of IGF1 to the tissues is modulated by IGF-binding proteins (IGFBPs), and higher circulating levels of IGF1 and lower levels of IGFBP3 have been reported in breast cancer patients." (PMID 9413957, 1997). "Evidence regarding IGFBP-3 gene polymorphisms’ implications in serum levels of IGFBP-3 and IGF-1 in the Gaza Strip and their association with breast cancer risk remains unclear." (PMID 40493660, 2025). "In another trial, the authors investigated the effects of melatonin on breast cancer markers [insulin-like growth factor 1 (IGF-1), estradiol, insulin-like growth factor-binding protein-3 (IGFBP-3), and IGF-1/IGFBP-3 ratio] in postmenopausal breast cancer survivors." (PMID 40001911, 2025). "This study examined the impact of insulin-like growth factor binding protein-3 (IGFBP-3) A-202C polymorphism (rs2854744) on breast cancer risk and its association with insulin-like growth factor-1 (IGF-1) and IGFBP-3 serum levels among Palestinian women in the Gaza Strip." (PMID 40493660, 2025). "Despite numerous investigations collectively indicating a link between the IGFBP-3 A-202C polymorphism and the risk of developing breast cancer, the results are still not conclusive." (PMID 40493660, 2025).
breast carcinoma (continued). "Higher IGF-1 and IGFBP-3 levels in CC genotype carriers could indicate enhanced tumorigenic pathways mediated through IGF signalling, potentially influencing breast cancer susceptibility and progression." (PMID 40493660, 2025). "MSCs have been reported to inhibit tumor progression via various paracrine factors in hepatocellular carcinoma, breast cancer, ovarian cancer, and glioma, these factors include insulin-like growth factor-binding protein 3, transforming growth factor-β and DKK1." (PMID 37287079, 2023). "IGFBP3 has been shown to be important in the development of colorectal and breast cancer." (PMID 36901940, 2023). "In the present study, we aimed to determine whether IGFBP-3 modulates telomerase activity in MCF-7 human breast cancer cells during senescence induction." (PMID 37253773, 2023). "Studies have demonstrated that low IGFBP-3 and high IGF-1 and IGFBP-2 levels are associated with high cancer risk, poor prognosis, and tumor metastasis in several cancers, including CRC, breast cancer, and prostate cancer; however, these findings remain controversial and can be population specific." (PMID 38137390, 2023). "Moreover, IGFBP3, the largest and most abundant circulating IGFBP, was initially found to be associated with breast cancer." (PMID 36997948, 2023). "Interestingly, NGS results show that miR-9 directly targets HMGA2, EGR1, and IGFBP3, which are closely related to the invasion and metastasis of breast cancer." (PMID 38132441, 2023). "Therefore, this meta-analysis will focus on the effects of exercise on IL-6, IL-10, IL-1β, CRP, TNF-α, IGF-1 and IGFBP-3 levels in breast cancer patients." (PMID 36482346, 2022). "Many previous studies suggested that the alteration of IGFBP3 could affect many types of tumors including hepatocellular carcinoma, breast cancer, and lung cancer." (PMID 36409444, 2022). "Energy homeostasis genes play an important role in carcinogenesis and their interactions with the serum concentrations of IGF-1 and IGFBP-3 on the risk of breast cancer have not yet been investigated." (PMID 35115550, 2022). "A 10 kg/m2 increase in BMI from age 18 was associated with a 13.4% increase in IGFBP‐3 gene expression among women with a positive family history of breast cancer and a 7.0% decrease among women with no family history of breast cancer (pinteraction = 0.02)." (PMID 35304837, 2022). "This suggests that lower PRMT6 expression may lead to increased expressions of PTEN and IGFBP3, decreased cell cycle progression and increased apoptosis of breast cancer cells." (PMID 35311114, 2022). "We hypothesized that we would observe an increased risk of breast cancer recurrence with elevated IGF-I and IGFBP-3 levels while elevated IGFBP-7 may confer better prognosis." (PMID 33767994, 2021). "Our purpose was to establish whether circulating IGF-I, IGFBP-3, and IGFBP-7 levels are related to recurrence-risk in breast cancer." (PMID 33767994, 2021). "There is prior evidence that systemic IGF-I and IGFBP-3 are associated with risk of breast cancer, but IGFBP-7 has not been studied in this context." (PMID 33767994, 2021). "The preoperative IGF-I and IGFBP-3 levels were prognostic indicators of breast cancer recurrence." (PMID 33767994, 2021). "Moreover, several studies have indicated that IGFBP3 exerts growth-stimulatory effects on many cancers, such as glioblastoma, breast cancer, prostate cancer and colorectal cancer 11,12." (PMID 34512163, 2021). "Therefore, high expression of DPPIV and reduced expression of IGFBP-3 point to reduced metastasis and proliferation of the breast cancer cells." (PMID 34228231, 2021). "No independent associations between IGFBP-7 or IGF-I/IGFBP-3 tertiles and breast cancer recurrence were observed (Ptrends>0.3)." (PMID 33767994, 2021).
breast carcinoma (continued). "IGFBP-3 inhibited the EGF-induced growth of breast cancer cells when cultured on plastic or laminin but could augment EGF-induced cell proliferation when cultured on fibronectin." (PMID 32478064, 2020). "Insulin-like growth factor binding protein 3 (IGFBP-3) plays a key role in breast cancer progression and was recently shown to bind to the chaperone protein glucose-regulated protein 78 (GRP78); however, the clinical significance of this association remains poorly investigated." (PMID 33352865, 2020). "The complexity of IGFBP-3 actions on breast cancer cells has long been acknowledged with reports of opposite effects and with the surrounding extracellular matrix microenvironment and changes in the sphingolipid rheostat having been described as underlying these different actions." (PMID 33352865, 2020). "The role of IGFBP-3 as a regulator of human breast cancer growth and survival is complex." (PMID 32478064, 2020). "Additionally, increased passage number of stably transfected IGFBP-3 in T47D cells showed increased growth, which indicates that breast cancers can alter their response to IGFBP-3 at different tumorigenicity." (PMID 32478064, 2020). "Studies using MCF-10A breast cancer cells demonstrated that IGFBP-3 leads to activation of EGFR, which could be internalized within the cells though caveolae-mediated endocytosis." (PMID 32478064, 2020). "Through a combination of in vitro experiments, clinical analyses and assessment of data from the publicly available METABRIC gene expression database, we have provided evidence that the interaction between GRP78 and IGFBP-3 plays major role in breast cancer progression and prognosis." (PMID 33352865, 2020). "With breast cancer cells, IGFBP-3 can promote cell survival of breast cancer cells when they were plated on fibronectin, that is representative of a more advanced cancer, but enhancing apoptosis when plated on collagen, that is representative of a more normal epithelial environment." (PMID 33352865, 2020). "Similar effect was observed in T47D, breast cancer cells stably transfected with IGFBP-3, where long-term cultures could induce cell growth, however, short-term cultures failed to induce growth." (PMID 32478064, 2020). "A study led by Baxter used breast cancer, T47D cells with Cy3-labeled transferrin and studied the effect on IGFBP-3 localisation in the presence of nocodazole and cholchicine, inhibitors of microtubule assembly, and chloroquine and monensin, lysomotrophic agents." (PMID 32478064, 2020). "Moreover, secretion of IGFBP‐3 by tumor vs stromal cells exhibited contrasting effects on breast cancer progression." (PMID 32767843, 2020). "Whilst both groups showed an interaction between GRP78 and IGFBP-3 using MCF-7 breast cancer cells they reported opposite functional consequences: one group showed this interaction resulted in increased survival, whereas the other showed that it culminated in an increase in apoptosis." (PMID 33352865, 2020). "We found an overall increased breast cancer risk for IGF-1 or IGFBP-3 elevation, although it was not statistically significant (≥ median compared to <: IGF-1 OR = 1.37, 95% CI = 0.66–2.85; IGFBP-3 OR = 1.62, 95% CI = 0.81–3.24)." (PMID 33092613, 2020). "Numerous researches have pointed out that the IGFBP3 overexpression is also in relation with the favorable survival in lung cancer, hepatocellular carcinoma, breast cancer, bladder carcinoma, esophageal squamous cell cancer, and pancreatic ductal adenocarcinoma." (PMID 33282953, 2020). "The association between IGFBP-3 and GRP78 that we observed in vitro was further supported by our clinical study in which we identified a positive correlation between GRP78 and IGFBP-3 in tumor samples from patients with breast cancers." (PMID 33352865, 2020). "Furthermore, several epidemiologic studies discovered an increased risk of breast cancer with higher levels of IGF-1 and the ratio of IGF-1 to IGFBP-3." (PMID 31816813, 2019).
breast carcinoma (continued). "In light of these findings, increased IGFBP-3 expression in breast cancer could represent a mechanism by which the surrounding stromal cells are attempting to induce apoptosis of tumors cells, which have found a way to evade this mechanism." (PMID 31693710, 2019). "Interestingly, it has been reported that PAI‐1 promotes senescence in MCF‐7 breast cancer cells by inhibiting tPA‐mediated proteolysis of IGFBP3." (PMID 28722352, 2017). "Thus, IGFBP3 is a poor marker for predicting breast cancer, although the relationship between HER2 and IGFBP3 expression warrants further investigation." (PMID 28081538, 2017). "We hypothesized that obesity will increase liver steatosis and DHEA treatment will protect against liver steatosis by reducing body weight gain and modulating serum IGF-1 and IGFBP-3 levels in breast cancer model." (PMID 28335515, 2017). "Our data indicate that targeting IGFBP-3-dependent signaling pathways through gefitinib-FTY720 co-therapy may be effective in many basal-like breast cancers, and suggest tissue IGFBP-3 and CD44 measurement as potential biomarkers of treatment efficacy." (PMID 28778177, 2017). "We found that increased levels of MTA1 correlate well with an elevated level of IGFBP3 as well as low DNMT3a and this may result in poor prognosis of breast cancer patients." (PMID 28393842, 2017). "In addition, MTA1 overexpression correlates well with low levels of DNMT3a which, in turn also correlates with a high IGFBP3 status in breast cancer patients and predicts a poor clinical outcome for breast cancer patients." (PMID 28393842, 2017). "Since IGF binding protein-3 (IGFBP-3) influences both breast cancer growth and adipocyte maturation, it may impact on how obesity promotes breast oncogenesis." (PMID 27448965, 2016). "In addition to being associated with both obesity and more aggressive breast cancer progression, PAI-1 is also involved in the induction of senescence through the regulation of IGFBP-3." (PMID 27448965, 2016). "Our study demonstrates that elevated IGF-I:IGFBP-3 ratios among women with biopsy-proven benign breast disease were associated with higher TDLU counts, a measure of decreased TDLU involution, which has been linked to increased breast cancer risk." (PMID 26893016, 2016). "In addition, IGFBP-3 has been shown in vitro to support breast cancer cell survival in response to hypoxia, glucose starvation and DNA-damaging agents." (PMID 27448965, 2016). "Similarly, the IGFBP3, IGF1R, IRS1, and PI3KCB genes have a purported relationship with breast cancer risk due to either their role in IGF1 signaling regulation, or association with strong breast cancer risk factors." (PMID 27376028, 2016). "Polymorphisms of IGF-1 and IGFBP-3 and environmental factors may work together to influence insulin-like growth factor (IGF) levels and thus breast cancer (BC) risk." (PMID 27631779, 2016). "Cumulative effects of IGFBP-3 rs2854744, DISI, and BMI on breast cancer risk." (PMID 27631779, 2016). "Within other types of cancer (e.g. prostate and breast cancer), the roles of IGFBP-3 and IGFBP-2 have been more thoroughly described, and demonstrated to convey both inhibitory and stimulating effects on tumor progression, depending on the tissue and type of cancer." (PMID 27111220, 2016). "This suggests that targeting IGFBP-3-dependent signaling pathways may be an effective approach to treating breast cancer in an obese environment." (PMID 27448965, 2016). "In conclusion, our results indicate that IGFBP-3 has a potentially stimulatory role in mammary tumor growth in vivo and may contribute to mammary tumor progression in the context of obesity." (PMID 27448965, 2016). "Therefore, this study used IGFBP-3-null mice to examine the influence of endogenous IGFBP-3 on both the development of obesity in response to high-fat feeding, and on subsequent mammary tumor growth." (PMID 27448965, 2016).
breast carcinoma (continued). "The clinical significance of these findings in the context of breast cancer is that IGFBP-3 and EGFR are relatively highly expressed in some aggressive ER-negative and PR-negative tumors that lack amplification of HER2, which are now referred to as triple-negative breast cancers, or TNBC." (PMID 26221601, 2015). "IGFBP-3 exerts both growth-stimulatory and apoptotic activity in breast cancer cells, and understanding how its expression is regulated by DNA-damaging agents has implications for predicting how IGFBP-3-expressing tumors may respond to chemotherapy." (PMID 26378048, 2015). "The expression of IGFBP-3 by breast cancer cells has been reported to correlate with ER status." (PMID 26378048, 2015). "In breast cancer, the data regarding IGFBP-3 are conflicting." (PMID 26217584, 2015). "Triple-negative breast cancer (TNBC) has high tumor expression of IGFBP-3 associated with markers of poor prognosis and, although accounting for 15–20% of all breast cancers, is responsible for disproportionate rates of morbidity and mortality." (PMID 26221601, 2015). "IGFBP-3 downregulation in some breast cancer cell lines in response to DNA-damaging chemotherapy may have clinical implications because suppression of IGFBP-3 may modulate the apoptotic response." (PMID 26378048, 2015). "IgfBp3 is well established as an inhibitor of breast cancer proliferation." (PMID 24658335, 2014). "The IGFBP3 long-range interaction profile was substantially altered in breast cancer." (PMID 24019942, 2013). "Taken together our results suggest a role for IGFBP-3 in 1, 25-D3 apoptotic signalling and impaired secretion of IGFBP-3 may be involved in acquired resistance to vitamin D in breast cancer cells." (PMID 23690781, 2013). "We hypothesized that cancer-related changes in IGFBP3 regulation and epigenetic modification might coincide with altered spatial positioning and long-range DNA interactions contributing to breast cancer pathogenesis." (PMID 24019942, 2013). "In Hs578T breast cancer cells, IGFBP3 promotes attachment and survival on fibronectin, which is present in the perivascular space of the brain microenvironment and known to promote the growth of breast cancer cells in the brain." (PMID 24039934, 2013). "Notably, there was a large increased relative risk of 7.3 for developing breast cancer in premenopausal women who were in the top tertile for high serum IGF-1 concentrations and had low circulating IGFBP3 concentrations." (PMID 23983688, 2013). "Strategies that deliver IGFBP3 as a therapy may benefit breast cancers that are resistant to trastuzumab and show elevated IGF-IR signaling." (PMID 22830017, 2012). "Analysis of the SNPs in IGF1 did not reveal any significant associations with any of the parameters studied (IGF1, IGFBP3, IGFratio or mammographic density), and thus we were unable to verify the previous findings regarding these SNPs and association to IGF1 levels and breast cancer risk." (PMID 20302654, 2010). "It seems that, at least in the current dataset, the IGFBP3 measures do not add substantial information in assessing the relationship of IGF1 with breast-cancer risk." (PMID 20472501, 2010). "Mammographic density, a strong risk factor for breast cancer, has been positively associated with the ratio of IGF1 to insulin-like growth factor binding protein (IGFBP)-3 in premenopausal women, and has been shown to modify the breast cancer risks in BRCA1 and BRCA2 mutation carriers." (PMID 19843326, 2009). "Results from a phase III breast cancer prevention trial with fenretinide, suggested that the reduction of IGF-I and IGFBP-3 levels may in part explain the cancer risk reduction observed in women ≤50 years of age." (PMID 22276018, 2009). "In summary, the impact of genetic variation in IGF1 and IGFBP3 on circulating IGF levels does not appear to substantially influence breast cancer risk substantially among primarily Caucasian postmenopausal women." (PMID 18596909, 2008).